UGT2B4 (UDP glucuronosyltransferase family 2 member B4)
Description:
UDP-glucuronosyltransferase (UGT) that catalyzes phase II biotransformation reactions in which lipophilic substrates are conjugated with glucuronic acid to increase the metabolite's water solubility, thereby facilitating excretion into either the urine or bile. Essential for the elimination and detoxification of drugs, xenobiotics and endogenous compounds. Catalyzes the glucuronidation of the endogenous estrogen hormones such as estradiol and estriol.
Synonyms: UGT2B11; HLUG25; UDPGT2B4; UDPGTH1; UDPGTh-1
Tractability: Antibody: UniProt predicts a signal peptide or a membrane-spanning region. PROTAC: its protein half-life has been measured.
Target class: Enzyme; Transferase
Gene: Protein-coding gene on chromosome 4 (69,480,137 to 69,526,017, reverse strand). Ensembl gene ENSG00000156096.
Subcellular location: Endoplasmic reticulum membrane
Pathways (Reactome):
Drug ADME: Aspirin ADME
Metabolism: Glucuronidation
Gene Ontology:
Molecular function: glucuronosyltransferase activity; retinoic acid binding; UDP-glycosyltransferase activity
Biological process: estrogen metabolic process; xenobiotic metabolic process
Cellular component: endoplasmic reticulum membrane
Genetic constraint (gnomAD): Loss-of-function variants: 43 observed, 46.55 expected, observed/expected ratio (o/e) 0.92, 90% interval 0.72 to 1.19. The upper end of that interval is the gene's LOEUF score, 1.19, which puts it in group 5 of 6, group 1 being the genes least tolerant of losing a copy. Missense variants: 691 observed, 618.65 expected, observed/expected ratio (o/e) 1.12, 90% interval 1.05 to 1.19. Synonymous variants: 228 observed, 214.08 expected, observed/expected ratio (o/e) 1.07, 90% interval 0.95 to 1.19.
Homologues: Orthologues: chimpanzee UGT2B4 (98% identical), zebrafish ugt2a7 (53% identical), zebrafish ugt2b5 (51% identical), zebrafish ugt2b1 (51% identical), zebrafish si:ch73-334d15.1 (42% identical), zebrafish ugt5a1 (41% identical), zebrafish ugt5a2 (41% identical), zebrafish ugt5g1 (41% identical), zebrafish ugt5b4 (39% identical), zebrafish ugt5b2 (38% identical), zebrafish ugt5f1 (38% identical), zebrafish ugt5c1 (38% identical), and 94 more. Paralogues in human: UGT2B11 (86% identical), UGT2B10 (86% identical), UGT2B7 (86% identical), UGT2B28 (84% identical), UGT2B15 (79% identical), UGT2B17 (78% identical), UGT2A3 (63% identical), UGT2A2 (63% identical), UGT2A1 (55% identical), UGT1A1 (45% identical), UGT1A3 (44% identical), UGT1A4 (44% identical), and 9 more.
Diseases named in the same sentence as UGT2B4 in open-access papers:
UGT2B4 is named in the same sentence as 26 diseases in open-access papers, as found by Europe PMC text mining. Sharing a sentence is not in itself a finding about the gene and the disease. The quoted sentences say what the papers report.
breast carcinoma (8 papers, 2010 to 2025). "Variations in the UGT2B4 gene are linked to an increased likelihood of developing pancreatic cancer and influence the pathological outcomes of chemotherapy in patients with breast cancer." (PMID 40108724, 2025). "Our previous work identified one region upstream human UGT2B4 (UDP glucuronosyltransferase family 2 member B4) which is associated with breast cancer and under balancing selection." (PMID 36823244, 2023). "For instance, the polymorphisms of UGT2B4 were reported to be associated with pancreatic cancer, breast cancer, and esophageal cancer." (PMID 37213709, 2023). "For example, other genes implicated by our genetic study, such as UGT2B4, might also be pharmacological targets for treating breast cancer." (PMID 20617168, 2010). "Our analysis showed that the expression level of UGT2B4 in breast cancer tumors was significantly lower than that in normal tissues, while UGT2B4 was significantly higher in tumors than in normal prostate cancer tissues." (PMID 33391440, 2021). "Our analysis showed that the expression level of UGT2B4 in tumors of breast cancer was significantly lower than normal tissues while UGT2B4 was significantly higher in tumors than normal tissues of prostate cancer." (PMID 33391440, 2021). "The associations in breast cancer survived correction for multiple testing of 15 genes (pglobal corrected = 0.045 for CYP19A1 and 0.03 for UGT2B4)." (PMID 20617168, 2010). "The UDP-glucuronosyltransferases UGT2B4 and UGT2B17 have been linked to breast cancer risk." (PMID 29743122, 2018). "We find that SPIN1 increases breast cancer Adriamycin resistance via enhancing the expression of drug metabolizing enzymes and transporter CYP2C8, UGT2B4, UGT2B17 and ABCB4." (PMID 29743122, 2018). "Data from PPISURV and GOBO revealed that breast cancer patients with high expression of ABCB4 (P = 0.0242), CYP2C8 (P = 0.02028), UGT2B4 (P = 0.0181) or UGT2B17 (P = 0.00815) showed poorer survival than those with low expression." (PMID 29743122, 2018). "Altogether these data indicate that the expression of the drug metabolizing enzymes CYP2C8, UGT2B4 and UGT2B17, and transporter ABCB4 was positively regulated by SPIN1 in breast cancer." (PMID 29743122, 2018). "SPIN1 is identified as a novel target of the miR-148/152 family and enhances Adriamycin resistance by regulating drug metabolizing enzymes and transporter CYP2C8, UGT2B4, UGT2B17 and ABCB4 in breast cancer." (PMID 29743122, 2018).
pancreatic cancer (4 papers, 2022 to 2025). "In the literature, the presence of the UGT2B4 rs1131878 heterozygote in comparison to both homozygotes increased the pancreatic cancer risk." (PMID 39596349, 2024). "In this context, overexpression of UGT2B isoforms (UGT2B4, 2BT, and 2B15) led to a significant diminution in cellular proliferation in breast and pancreatic cancer cells in association with a decrease in lipids content." (PMID 35626664, 2022).
Cirrhosis (3 papers, 2021 to 2025). A chronic disorder of the liver in which liver tissue becomes scarred and is partially replaced by regenerative nodules and fibrotic tissue resulting in loss of liver function. "Targets affected only by NAFLD-associated cirrhosis were CYP2C8,MGST1, MGST3, UGT2B4, FMO5, and BSEP, while targets that showed asignificant reduction only with cancer-associated cirrhosis were CYP2E1and UGT1A6." (PMID 34428046, 2021).
colorectal cancer (3 papers, 2017 to 2024). A primary or metastatic malignant neoplasm that affects the colon or rectum. "Also, the pharmacogenetic study of Scherer’s group presented the correlations of UGT2B4 rs1131878 heterozygotes with lower risk of colorectal cancer in users of nonsteroidal anti-inflammatory drugs than nonusers with only major alleles." (PMID 39596349, 2024). "In a study of 1600 colorectal cancer patients and 2500 unaffected siblings, the variation in 4 UGT genes (UGT1A3, UGT1A6, UGT2B4, and UGT2B15) modified risk of colorectal cancer either independently of interactively with nonsteroidal anti-inflammatory use." (PMID 27881391, 2017).
cholestasis (2 papers, 2018 to 2021). Impairment of the bile flow caused by obstruction within the liver, or outside the liver in the bile duct system. "Cancer and/or non-alcoholicfatty liver disease-related cirrhosis showed larger deteriorationin levels of CYP3A4, 2C8, 2E1, 1A6, UGT2B4/7, CES1, FMO3/5, EPHX1,MGST1/3, BSEP, and OATP2B1 than the cholestasis set." (PMID 34428046, 2021). "Changes in the expression of genes indicative of cholestasis represented changes in the transporters ABCC2 and UGT2B4, which are up-regulated by the farnesoid X receptor and are involved in the glucuronidation of the bile acid hyodeoxycholic acid." (PMID 30572671, 2018).
lung adenocarcinoma (2 papers, 2023 to 2024). A carcinoma that arises from the lung and is characterized by the presence of malignant glandular epithelial cells. "Rs11723463 is associated with UGT2B4 expression in LUSC (lung squamous cell carcinoma; P = 7.54 × 10–18), LUAD (lung adenocarcinoma; P = 5.0 × 10–15) and BRCA (breast invasive carcinoma; P = 1.5 × 10–7) tissues." (PMID 36823244, 2023).
malignant ovarian tumors (2 papers, 2024). "Miscellaneous diseases and traits that were associated with UGT2B4 were bacteremia, color vision defects, and malignant ovarian tumors." (PMID 39457450, 2024).
prostate carcinoma (2 papers, 2021 to 2022). A carcinoma that arises from epithelial cells of the prostate gland. "We found that high expression of UGT2B4 was associated with low-grade prostate cancer and upregulation of UGT2B4 in tumors was associated with upregulation of metabolism pathways such as 'de novo' IMP biosynthetic process, glutamine and monocarboxylic acid metabolism." (PMID 33391440, 2021). "Furthermore, we found that high expression of UGT2B4 was associated with low-grade prostate cancer and favorable disease-free survival." (PMID 33391440, 2021). "To examine the functional mechanism of UGT2B4 expression in prostate cancer, we investigated the expression data of a pan-cancer study from TCGA." (PMID 33391440, 2021). "The results showed that a region in chromosome 4q13.2 which contains multiple UDP glucuronosyltransferase family genes was amplified in 20% of Sardinian prostate cancers and the amplified peak was centered on UGT2B4." (PMID 33391440, 2021). "To examine the impact of UGT2B4 expression in prostate cancer, we investigated the expression data of pan-cancer study from TCGA." (PMID 33391440, 2021). "To examine the clinical relevance of UGT2B4 in prostate cancer, we downloaded gene expression profiles and clinical profiles of 497 tumors from primary prostate cancer patients in The Cancer Genome Atlas (TCGA) database." (PMID 33391440, 2021). "Further to examine the potential functional mechanism of UGT2B4 in prostate cancer, we performed the spearman correlation analysis of UGT2B4 in the expression data of the 497 prostate cancer patients from TCGA." (PMID 33391440, 2021). "In addition, we examined the expression of UGT2B4 in 497 prostate cancer patients derived from The Cancer Genome Atlas database." (PMID 33391440, 2021). "In addition, our analysis provides insight into clinical relevance and functional mechanism of UGT2B4 expression in prostate cancer." (PMID 33391440, 2021). "Further understanding functional mechanism of UGT2B4 amplification and BTBD7-SLC2A5 fusion will aid in developing drugs to benefit the prostate cancer patients." (PMID 33391440, 2021).
anemia (1 paper, 2024). A reduction in the number of red blood cells, the amount of hemoglobin, and/or the volume of packed red blood cells. "Reported in the current study, UGT2B4 rs1131878 common homozygote AA was the independent predictor of recurrent anemia while the presence of heterozygote AG was the independent predictor of recurrent neutropenia, including severe symptoms." (PMID 39596349, 2024).
neutropenia (1 paper, 2024). A decrease in the number of neutrophils found in the blood. "In our study, the risk of severe recurrent neutropenia (grades 3 and 4) was independently influenced by the ABCB1 rs17064 genotype AT (OR 5.13; 1.38–19.02; p = 0.014), UGT2B4 rs1131878 genotype AG (OR 3.78; 1.26–11.24; p = 0.016), and ALDH5A1 genotype AC (OR 3.94; 1.34–11.53; p = 0.012)." (PMID 39596349, 2024).
Obesity (1 paper, 2025). Accumulation of substantial excess body fat. "The increased function of UGT2B4 could contribute to the lower AUC0-inf of lorazepam observed in the population with obesity." (PMID 40359692, 2025).
prostate tumours (1 paper, 2020). "Similar to normal prostate tissue, prostate tumours expressed several UGT2B mRNAs, including UGT2B17 but also UGT2B4, UGT2B7, UGT2B10, UGT2B11, UGT2B15 and UGT2B28." (PMID 32047296, 2020).
cancer (7 papers, 2010 to 2025). A tumor composed of atypical neoplastic, often pleomorphic cells that invade other tissues. "Recent transcriptomic analyses have further expanded the biological significance of UGT2B4 in cancer." (PMID 40612672, 2025). "As canagliflozin is metabolized and excreted by UGT1A9 and UDP glucuronosyltransferase family 2 member B4 (UGT2B4), we speculate that cancer cells expressing SGLT2 combined with low levels of UGT1A9 and UGT2B4, will make these tumor cells sensitive to canagliflozin." (PMID 31979355, 2020).
tumor (4 papers, 2020 to 2025). "As well, we found that high expression of UGT2B4 was associated with upregulated tumor metabolic pathways such as 'de novo' IMP biosynthetic process, glutamine and monocarboxylic acid metabolism." (PMID 33391440, 2021). "Functional enrichment analysis reveals that UGT2B4 co-expression genes enriched in tumor metabolic pathways such as 'de novo' IMP biosynthetic process, glutamine and monocarboxylic acid metabolic." (PMID 33391440, 2021). "Single-cell expression analysis revealed that KRT5 and FABP7 were highly enriched in tumor cells, UGT2B4 was predominantly expressed in epithelial cells, BIRC3 and KLRB1 were enriched in CD8+ T cells, while MRC1 and CD209 were highly expressed in monocytes/macrophages." (PMID 40612672, 2025). "We found that the expression of UGT2B4 was positively associated with expression of multiple well-known oncogenes such as SPINK1, IDH1, MYC, and SRC and negatively associated with expression of well-known tumor suppressors such as CIC and ERF." (PMID 33391440, 2021).
UGT2B4 also shares sentences with these, for which no sentence is quoted: ovarian carcinoma (2 papers); bacteremia (1); breast invasive carcinoma (1); cutaneous melanoma (1); esophageal cancer (1); hepatocellular carcinoma (1); Hypertension (1); liver cancer (1); lung squamous cell carcinoma (1); metabolic dysfunction-associated steatotic liver disease (1); type 2 diabetes mellitus (1); uveal melanoma (1).